CXCR4 (C-X-C motif chemokine receptor 4)
Diseases named in the same sentence as CXCR4 in open-access papers (continued):
Sharing a sentence is not in itself a finding about the gene and the disease.
WHIM syndrome (continued). "As of December 6, 2023, ClinVar contained entries for 19 of the 36 CXCR4 variants that have been identified in individuals with WHIM syndrome in scientific literature, with 15 of them classified as likely pathogenic or pathogenic, 4 as variant of uncertain significance." (PMID 39040098, 2024). "In this review, we aim to summarize the current knowledge of the landscape of CXCR4 variants in WHIM syndrome, as well as provide an overview of functional assays that can support interpretation of newly discovered CXCR4 variants and their pathogenic role in the disease." (PMID 39040098, 2024). "WHIM Syndrome is a rare immunodeficiency caused by gain-of-function CXCR4 mutations." (PMID 37045841, 2023). "Impaired downregulation of C-terminus–mutated CXCR4 after agonist stimulation is commonly postulated to account for the increased receptor signaling and function, which was proposed as a pathogenic mechanism operating in WHIM syndrome." (PMID 36883568, 2023). "In this regard, it is noteworthy that CXCR4 GOF heterozygous dominant mutations are responsible for the rare human immunodeficiency WHIM syndrome (for Warts, Hypogammaglobulinemia, Infections, and Myelokathexis) featured by a panleukopenia and selective susceptibility to HPV-induced pathogenicity." (PMID 35159113, 2022). "Previous studies have noted that CXCR4 mutations involved in WHIM syndrome have enhanced signaling." (PMID 34973340, 2022). "Moreover, CXCR4 mutations found in WHIM syndrome also occur in ∼30% of the cases of the plasma cell cancer Waldenstrom’s macroglobulinemia." (PMID 34973340, 2022). "Greater than 85% of patients with WHIM syndrome harbor heterozygous CXCR4 mutations." (PMID 36089616, 2022). "In WHIM syndrome, gain-of-function mutations in the chemokine receptor CXCR4 may provide conditions supportive of oncogenic transformation." (PMID 33918597, 2021). "Up to now, 105 cases of WHIM syndrome have been described all over the world, and almost all of them were caused by different mutations causing truncation of the C-terminus of CXCR4, losing phosphorylation sites, but only one missense mutation in CXCR4, and all potential phosphorylation are intact." (PMID 33485325, 2021). "These mutations closely resemble those occurring in Warts, Hypogammaglobulinemia, Immunodeficiency, and Myelokathexis (WHIM) syndrome, an immunodeficiency associated with CXCR4 aberrant expression and activity and with chemotherapy resistance in clinical trials." (PMID 32260318, 2020). "Defects in CXCR4 desensitization alone can cause numerous physiological defects in hematopoietic cell development and recirculation that result in immune deficiency, as evidenced by patients afflicted with WHIM syndrome." (PMID 33324418, 2020). "All but a few cases of WHIM syndrome are caused by autosomal dominant gain-of-function mutations in the G protein-coupled, cysteine-X-cysteine chemokine receptor CXCR4, and these are the only chemokine or chemokine receptor mutations responsible for a Mendelian condition." (PMID 30577453, 2018). "Warts, hypogammaglobulinemia, infections, and myelokathexis (WHIM) syndrome is a rare, autosomal dominant, combined immunodeficiency disorder caused by mutations in the C-terminus of CXCR4 that prevent receptor downregulation and therefore result in pathologically increased signaling." (PMID 30577453, 2018). "However, the hyperfunctional CXCR4 that causes the WHIM syndrome delivers aberrant signals to T cells." (PMID 28928741, 2017). "Here, we thought to investigate this issue by providing mechanistic insights into the selective susceptibility to HPV pathogenesis displayed by patients who are immunosuppressed as a consequence of mutations in the CXCR4 gene encoding for the receptor of the CXCL12 chemokine (WHIM syndrome)." (PMID 27918748, 2016).
WHIM syndrome (continued). "Similarly, NK cells from mice displaying the most common mutation of the CXCR4 gene associated with WHIM syndrome show enhanced migration to CXCL12 that is linked to impaired CXCR4 desensitization and internalization after CXCL12 stimulation." (PMID 27766097, 2016). "However, the embryonic lethality of CXCR4-ΔT mice was unexpected, as patients with WHIM syndrome who also harbor truncating mutations at the CXCR4 C-terminus exhibited a dominant gain of function phenotype." (PMID 21124917, 2010). "Blocking of the CXCL12/CXCR4 signaling axis leads to the proliferation of primitive hematopoietic stem cells while excessive signaling by CXCR4 accounts for the molecular pathoetiology of the WHIM syndrome and is associated with tumor growth and metastasis formation." (PMID 20161793, 2010). "The majority of patients with WHIM syndrome have been linked to heterozygous genetic mutations in the gene encoding CXCR4 resulting in truncations of the cytosolic carboxy-terminal portion of the receptor and thus co-express the normal and mutant CXCR4 proteins." (PMID 19956569, 2009). "Here, we investigated the biochemical mechanisms underlying CXCR4 deficiency in WHIM syndrome." (PMID 19956569, 2009). "For the CXCL12–CXCR4 axis, the CXCR4 antagonist mavorixafor, which mobilizes stem and endothelial progenitor cells, is under investigation for harnessing this reparative potential; however, only in patients with WHIM syndrome, a rare immunodeficiency caused by gain-of-function of CXCR4 gene." (PMID 40986007, 2025). "In addition, a patient with WHIM with warts was cured as an adult of WHIM syndrome by chromothriptic deletion of the disease allele solely in her myeloid lineage, which suggests that plerixafor might also benefit warts by blocking CXCR4 on myeloid cells." (PMID 37561579, 2023). "WHIM syndrome (warts, hypogammaglobulinemia, infections, myelokathexis) is a rare multi-system combined immunodeficiency most often caused by autosomal dominant pathogenic variants in the CXCR4 gene region coding for the C-terminus of the C-X-C chemokine receptor type 4." (PMID 35947323, 2022). "Studies have clarified that the loss of phosphorylation sites in the C-terminus of truncated CXCR4 impairs the desensitization process, enhances the activation of G-protein, prolongs downstream signaling pathways and introduces over immune responses, thereby causing WHIM syndrome." (PMID 33485325, 2021). "Therefore, high expression of CXCR7 in tumor cells may contribute to excessive signaling through CXCR4, a landmark of the pathophysiology of WHIM syndrome, which is also associated with tumor growth and metastasis formation." (PMID 22457824, 2012). "The top predicted drug is Mavorixafor, which is a known oral CXCR4 antagonist used to treat WHIM syndrome." (PMID 41256885, 2025). "Targeted deletion of Cxcr4 results in severe disorganization of the cerebellum while Cxcr4 overactivation results in foliation defects which are also observed in human warts hypogammaglobulinemia immunodeficiency myelokathexis (WHIM) syndrome patients." (PMID 41278839, 2025). "Mavorixafor, an orally bioavailable CXCR4 antagonist, has shown meaningful increases in absolute neutrophil count and reduced infections in WHIM syndrome patients." (PMID 41451234, 2025). "Our previous studies support this argument, demonstrating that the CXCR4 antagonist effectively mobilizes neutrophils while preserving their effector functions in a mouse model of WHIM syndrome as well as in patients with chronic neutropenia." (PMID 41451234, 2025). "CXCR4 hyperactivation in WHIM syndrome traps neutrophils and monocytes in bone marrow through excessive SDF-1 binding." (PMID 41141324, 2025). "Cxcr4+/1013 mice exhibited profound peripheral blood leukopenia as seen in patients with WHIM syndrome." (PMID 39588369, 2024). "The current data presented here with Cxcr4+/1013 mice corroborated these previous observations in patients with WHIM syndrome." (PMID 39588369, 2024).
WHIM syndrome (continued). "Recent efforts investigating gene therapy as a curative treatment for WHIM syndrome have shown that leukopenia correction can be achieved in unconditioned WHIM mice by CXCR4-haploinsufficient bone marrow transplant." (PMID 39226327, 2024). "In the phase 3 trial in patients with WHIM syndrome, treatment with CXCR4 antagonist mavorixafor increased and corrected peripheral blood CD4+ and CD8+ T-cell lymphopenia." (PMID 39588369, 2024). "The impact of CXCR4 antagonism on other aspects of the pathobiology in WHIM syndrome, such as lymphopoiesis and leukocyte trafficking between primary and secondary lymphoid organs, is less understood." (PMID 39588369, 2024). "Our study provides comprehensive evidence that oral dosing with a CXCR4 antagonist can effectively correct WHIM-associated neutrophil and lymphocyte abnormalities in a mouse model of WHIM syndrome." (PMID 39588369, 2024). "A functional cure of WHIM syndrome has been reported in a patient following chromothriptic deletion of the abnormal CXCR4 gene in hematopoietic stem cells, suggesting the potential of gene editing as a future therapeutic approach." (PMID 39035006, 2024). "The CXCR4 antagonist plerixafor mobilizes leukocytes to the blood; however, its safety and efficacy in WHIM syndrome are undefined." (PMID 37561579, 2023). "Using a mouse model harboring a WHIM Syndrome-linked gain-of-function CXCR4 mutation and bone marrow samples from WHIM patients, the authors show that proper CXCR4 signaling termination is essential for bone tissue homeostasis." (PMID 37045841, 2023). "She subsequently experienced one other psoriasis flare over 5 years since the end-of-study visit, during a phase II clinical trial for WHIM syndrome of the chemically distinct small-molecule CXCR4 antagonist mavorixafor." (PMID 37561579, 2023). "In summary, we generated the first cellular model that recapitulates both the genetic changes in WHIM syndrome as well as the CXCR4 desensitization defect paralleled by the GOF phenotype in downstream signaling assays." (PMID 36089616, 2022). "While C-terminal truncations and mutations in CXCR4 have been shown to enhance CXCR4 signaling and lead to WHIM syndrome, we still have an incomplete picture of how these changes alter CXCR4 function." (PMID 34973340, 2022). "The majority of the newly identified CXCR4 variants showed defects in CXCL12-induced internalization comparable to R334*, the most frequent and most studied WHIM syndrome variant." (PMID 35947323, 2022). "In cases of WHIM syndrome with CXCR4 gain-of-function (GOF) variants, CXCR4 internalization is decreased, thus prolonging the interaction of CXCR4 and its ligand CXCL12, leading to hyperactive signaling." (PMID 35947323, 2022). "Warts, hypogammaglobulinemia, infections, and myelokathexis (WHIM) syndrome is a rare autosomal dominant primary immunodeficiency (PID), caused by CXCR4 gene mutations." (PMID 34697698, 2022). "Overall, both cellular models recapitulate well the impaired CXCR4 internalization and hyperactive receptor signaling found in immune cells from patients with WHIM syndrome." (PMID 36089616, 2022). "Mavorixafor is a potent and selective investigational CXCR4 antagonist currently being studied in clinical trials for the treatment of patients with WHIM syndrome (NCT03005327)." (PMID 36089616, 2022). "Along with this phosphorylation pattern, investigations of the pathogenesis of WHIM syndrome permitted us to assign a major role to GRK3 in regulating CXCL12-induced desensitization of CXCR4." (PMID 33466410, 2021). "The E343K mutation impairs the desensitization and the down-stream signal transduction of CXCR4, consequently lead to WHIM syndrome." (PMID 33485325, 2021). "AMD3100 (Plerixafor) is a CXCR4 antagonist that successfully corrects circulating numbers of neutrophils in neutropenic patients with WHIM syndrome that has been approved for clinical use." (PMID 33240898, 2020).
WHIM syndrome (continued). "Therefore, we explored whether mRNA electroporation of CXCR4, including the WHIM syndrome naturally occurring GOF mutated variant CXCR4R334X, could be utilized to improve NK cell in vitro migration toward its ligand stromal-derived factor-1α (SDF-1α) and in vivo homing to BM compartments in mice." (PMID 31231387, 2019). "Therefore, we explored whether mRNA electroporation of CXCR4, including the WHIM syndrome naturally occurring GOF mutated variant CXCR4R334X, could be utilized to improve NK cell in vitro migration toward its ligand SDF-1α and in vivo homing to BM compartments in mice." (PMID 31231387, 2019). "Disruption of the CXCR4/CXCL12 balance such as that found in WHIM syndrome (Warts, Hypogammaglobulinemia, Immunodeficiency, and Myelokathexis syndrome) leads to deregulated neutrophil release into the circulation." (PMID 30356867, 2018). "From previous analyses of neutrophils derived from patients suffering from the WHIM syndrome it is anticipated that Cxcr4+/1013neutrophils would be also prone to an enhanced Cxcl12-dependent chemotaxis." (PMID 27111140, 2016). "The cytoplasmic tail of CXCR4 is truncated in WHIM syndrome, resulting in reduced internalization,higher number of CXCR4 surface receptors, and enhanced chemotaxis of leukocytes in response to CXCL12." (PMID 25909600, 2015). "This is analogous to reports of enhanced chemotaxis with higher cell surface CXCR4 in the pathological setting of WHIM syndrome (warts, hypogammaglobulinemia, infections, and myelokathexis)." (PMID 25909600, 2015). "Current concepts for the genesis of WHIM syndrome focus on disturbances in the CXCR4 C-terminal phosphorylation and ß-arrestin recruitment events." (PMID 23734232, 2013). "A particular feature of the WHIM syndrome CXCR4 mutant receptors is a delay in the receptor sequestration that follows CXCL12 exposure, and substantial evidence has been presented that WHIM receptors are gain-of-function mutants causing prolonged signaling." (PMID 23734232, 2013). "Leukocytes from patients with WHIM syndrome display impaired CXCR4 internalization and enhanced chemotaxis in response to its unique ligand SDF-1/CXCL12, which likely contribute to the clinical manifestations." (PMID 19956569, 2009). "Since β-Arrestins and Grks play critical roles in phosphorylation and internalization of agonist-activated G protein-coupled receptors, these results provide a molecular basis for CXCR4 dysfunction in WHIM syndrome." (PMID 19956569, 2009). "To define the molecular basis for WHIM syndrome, we generated HeLa cell lines that stably expressed either wild-type (WT) CXCR4 or a mutant CXCR4 with a 19 amino acid truncation at the carboxy-terminus." (PMID 19956569, 2009). "Our findings in CXCR2 LOF mice are consistent with previous reports in patients with WHIM syndrome indicating that CXCR4 antagonist treatment results in clinically significant improvements in peripheral blood neutrophil levels and reductions in infection rates." (PMID 41451234, 2025). "Currently there are two CXCR4 antagonists in clinical trials for treating WHIM syndrome." (PMID 39226327, 2024). "In favor of such an interpretation was the observation that in CXCR4+/1013 mice with a heterozygous CXCR4 gain of function mutation characteristic of WHIM syndrome, remyelination was observed even in the absence of testicular T." (PMID 38291527, 2024). "In summary, this study provides more comprehensive evidence that CXCR4 antagonism can effectively correct WHIM-associated neutrophil and lymphocyte abnormalities in primary and secondary lymphoid organs in a mouse model of WHIM syndrome." (PMID 39588369, 2024). "Another promising CXCR4 antagonist for WHIM syndrome is Plerixafor (Mozobil, AMD3100)." (PMID 39226327, 2024).
WHIM syndrome (continued). "As CXCR4 GOF mutations play a central role in the pathogenesis of WHIM syndrome, correction of aberrant CXCR4 signaling using CXCR4 antagonists including plerixafor and mavorixafor has been explored as a potential therapeutic approach for the treatment of WHIM syndrome." (PMID 39588369, 2024). "Our data provide additional evidence to support the notion that CXCR4 antagonist treatment effectively mobilizes more functional neutrophils, that may, in turn, help patients with WHIM syndrome to overcome the recurrent infections commonly observed." (PMID 39588369, 2024). "Conversely, our results show how WHIM syndrome can be caused by CXCR4 variants that do not behave as gain-of-function mutations, underlying the need for functional characterization of novel genetic variants to explore patient-targeted therapeutic strategies." (PMID 36883568, 2023). "This work may open avenues for reclassification of variants of uncertain significance, providing a major leap forward in diagnosing and treating WHIM syndrome, WM, and other CXCR4-dependent PID diseases." (PMID 36089616, 2022). "Lymphopenias may also occur in WHIM syndrome, yet disproportionate susceptibility to HPV versus other lymphopenic disorders may suggest specific susceptibility in WHIM, namely the CXCR4 gain‐of‐function mutation." (PMID 35665206, 2022). "The CXCR4 orthosteric antagonist Plerixafor was the first chemokine receptor antagonist to be approved in lymphoma and myeloma and is currently being tested in other cancers, as well as in WHIM syndrome patients to treat HPV-induced lesions." (PMID 35159113, 2022). "While several gain-of-function mutations that lead to C-terminal truncations, frame shifts and point mutations in the chemokine receptor CXCR4 have been identified in WHIM syndrome patients, the functional effect of these mutations are not fully understood." (PMID 34973340, 2022). "Importantly, pharmacologic CXCR4 antagonism reduced gamma HPV predominance in patients with WHIM syndrome over time in a clinical trial, a potential target for wart treatment." (PMID 35665206, 2022). "Taken together, WT CXCR4 and all tested CXCR4WHIM variants were sensitive to pharmacological intervention with mavorixafor at drug concentrations used in clinical trials of patients with WHIM syndrome." (PMID 36089616, 2022). "Taken together, these studies identify a new WHIM syndrome mutant, CXCR4-S339fs5, which promotes enhanced signaling, reduced phosphorylation, β-arrestin binding and endocytosis, and a very high basal rate of degradation that is not protected by antagonist treatment." (PMID 34973340, 2022). "To better understand the characteristics of S339fs5 that might contribute to its role in WHIM syndrome, we generated a stable cell line expressing S339fs5 and compared its properties with wild-type (WT) CXCR4 and with another WHIM syndrome mutant, R334X." (PMID 34973340, 2022). "In this manuscript, we show for the first time that ex vivo expanded NK cells isolated from the circulation of patients with WHIM syndrome have stronger BM homing potential in vivo when infused into immunodeficient mice compared to NK cells expanded from healthy donors expressing WT CXCR4." (PMID 31231387, 2019). "The non-canonical signaling of truncated GOF CXCR4 variants is well-characterized within the context of WHIM syndrome and Waldenström's macroglobulinemia, where the hyperfunctional phenotype of truncated CXCR4 results in sequestration of cells in BM niches." (PMID 31231387, 2019). "CXCR4 has been associated with several diseases, including human immunodeficiency virus (HIV) infection, cancer, warts, hypogammaglobulinemia, immunodeficiency, myelokathexis (WHIM) syndrome, pulmonary artery hypertension (PAH), and pulmonary injury." (PMID 30791675, 2019).